CD44 (CD44 molecule (IN blood group))
Diseases named in the same sentence as CD44 in open-access papers (continued):
Sharing a sentence is not in itself a finding about the gene and the disease.
glioma (continued). "CD44 and OPN were found to colocalize in the perivascular niche (where stem-like glioma cells reside), so the question of whether OPN activated CD44 to cause a stem-like phenotype was asked." (PMID 33203146, 2020). "BMI1 and CD44 were reported to differentiate the mesenchymal molecular subtype from other gliomas." (PMID 33329553, 2020). "The authors performed the meta-analyses to study the prognostic significance of CD44 in gliomas and concluded that high expression of CD44 might predict poor survival in glioma, particularly in WHO grade II–III gliomas." (PMID 33030522, 2020). "Thus, when examining the prognostic significance of CD44 in gliomas, the cut-off value of CD44 expression should be defined separately, depending on the grade of the gliomas." (PMID 33030522, 2020). "OPN signaling via CD44 was found to promote aggressive glioma growth and stem cell phenotypes." (PMID 33203146, 2020). "The brain is comparatively abundant in hyaluronic acid, suggesting that CD44 may be an important mediator of glioma cells’ migration inside the brain." (PMID 32429463, 2020). "Taken together, these results demonstrated that higher tumor expression of CD44 may predict poor survival in patients with glioma, particularly in those with WHO stage II–III glioma." (PMID 32232385, 2020). "It was shown that CD44 modulates the hypoxic response of glioma cells and that the pseudo-hypoxic phenotype of stem-like glioma cells is achieved by stabilization of hypoxia-inducible factors-2α through interaction with CD44, thereby contributing to the stemness of glioma cells." (PMID 32232385, 2020). "However, two major defects exist in the present study, which made the meta-analysis on the prognostic significance of CD44 in all gliomas unreliable." (PMID 33030522, 2020). "Valproic acid, an effective antiepileptic drug, exerts a potential anti-GBM effect via the inhibition of angiogenesis and the downregulation of 0-6-methylguanine-DNA methyltransferase (MGMT) expression, which has been found to decrease CD44 expression in several glioma cell lines." (PMID 33322363, 2020). "CD44 expression was previously reported to promote BMSC migration toward gliomas." (PMID 32452829, 2020). "Like HA, CD44 was enriched in the glioma with low expression in normal brain." (PMID 32190011, 2020). "Finally, the potential therapeutic significance of CD44 as a treatment target for glioma also should be determined in the future." (PMID 32232385, 2020). "However, CD44-high glioblastoma is different from the general cases of glioma; it is classified as the mesenchymal subclass within glioblastoma." (PMID 32857809, 2020). "In glioma perivascular niche, osteopontin was demonstrated to promote stem cell-like properties, as well as radiation resistance in adjacent tumor cells via the activation of CD44 signaling." (PMID 33374813, 2020). "Among the various types of gliomas, CD44 is expressed with the highest expression of 55.55% in GBM." (PMID 32429463, 2020). "Western blotting analyses of Fatty Acid Synthase, FASN, and CD44 resulted in effective inhibition of these markers after CCT treatment, which was associated with important activation of the apoptosis program and reduced glioma cell movement and wound repair." (PMID 31936544, 2020). "Thus, more studies are needed to further explore the relationship between CD44 gene/protein expression and grade IV gliomas." (PMID 33030522, 2020). "In addition to bulk evidence suggesting CD44 as a stem cell marker in various malignancies, including gliomas, recent scRNA-seq studies identified CD44 as a marker for a distinct lineage of glioma CSC-enriched populations." (PMID 33291443, 2020). "Therefore, we performed a meta-analysis to quantitatively summarize the predictive power of tumor CD44 expression for OS in patients with glioma." (PMID 32232385, 2020).
glioma (continued). "Indeed, compared to other proteoglycans rVAR2 binding and CD44 showed a strong co-localization on each evaluated glioma cell line (p < 0.001, one-way ANOVA)." (PMID 31466397, 2019). "In this study, the use of MDC in the treatment of CD44+ glioma cells has been extended in vivo." (PMID 30691081, 2019). "Even so, the role of CD44 remains ambivalent in glioma cell migration." (PMID 31003495, 2019). "We observed that galangin inhibited the proliferation, migration, invasion and angiogenesis of glioma cells in a dose-dependent manner, suppressed the expression of CD44 and inhibited angiogenesis of glioma cells through downregulating vascular endothelial growth factor (VEGF) in HUVECs." (PMID 31528214, 2019). "In this study, we aimed to investigate whether galangin can inhibit EMT, angiogenesis and CD44 expression in glioma." (PMID 31528214, 2019). "In addition, the overexpression of CD44 in U87 and U251 cells partly abolished the effects of galangin on glioma cells." (PMID 31528214, 2019). "Based on these, we hypothesized that CD44, overexpressed on TAMs and CSCs, as well as VMs, could be used as the target site for anti-glioma requirements." (PMID 29378465, 2018). "Also, typically with high glioma grade, the HA's cellular receptor CD44 is overexpressed, suggesting that CD44-enriched cells invade more efficiently the brain parenchyma." (PMID 30320080, 2018). "Hyaluronan and CD44 have been shown to promote glioma cell invasion, migration and adhesion." (PMID 29914429, 2018). "Therefore, co-expression of ALDH1A3 and a well-known MES differentiation marker CD44 in glioma cells reveals its potential as a MES marker." (PMID 30538217, 2018). "CD44 is a transmembrane glycoprotein expressed on normal cells and overexpressed in glioma cells." (PMID 30304861, 2018). "Inhibition of either CD44 or integrin receptors also limits glioma invasion in vivo and in vitro." (PMID 30451884, 2018). "In spite this tendency of glioma stem cells to exhibit a proneural signature, some glioma stem lines preferentially express mesenchymal markers: the mesenchymal stem cell lines are CD44+, exhibit low CD15 and OLIG2 expression and are characterized by a high radioresistance." (PMID 30279357, 2018). "miR-328 suppresses the survival of cancer cells by targeting PLCE1 in esophageal cancer, inhibits epithelial to-mesenchymal transition in renal tubular cells by targeting CD44, and regulates cell invasion and proliferation in glioma cells by targeting SFRP1 and in melanoma cells by targeting TGFb2." (PMID 29374351, 2018). "The detection of these proteins together to stem cell markers (CD133, CD44, and Sox2) may help to discriminate glioma cells to glioma stem-like cells." (PMID 29486795, 2018). "Moreover, CD133+ and CD44+ cells can be found simultaneously in xenotransplants generated from patients-derived glioma cells." (PMID 29259986, 2017). "To assess the functional significance of the relative overexpression of APOEC3G in CD44+ mesenchymal glioma cells compared with CD44− glioma cells, we depleted APOBEC3G expression using lentivirus expressing shRNA directed against APOBEC3G in A172, U343, and GSC20 cells." (PMID 28903341, 2017). "The apoptotic cells expressed the glioma marker CD44, indicating the cells are glioma cells." (PMID 28002799, 2017). "Also serglycin both from the glioma cells and MCs, via its interaction with CD44, can enhance growth, survival and differentiation of the cancer cells." (PMID 28445977, 2017). "Moreover, Cheng and co-workers found that the 64 gene signature is strongly correlated in gliomas with the putative stem cell marker CD44, and is highly enriched among the differentially expressed genes in glioblastomas vs. lower grade gliomas." (PMID 28279210, 2017). "Activation of CD44 by hyaluronic acid was shown to increase glioma cell invasion." (PMID 28380429, 2017).
glioma (continued). "Despite different cell sources of SPP1/osteopontin (whether SPP1 is produced by tumour or stromal cells) all presented data confirmed the important role of osteopontin-CD44 interactions in maintaining the glioma stem cell phenotype." (PMID 28030801, 2017). "CD44 is a cell-surface glycoprotein, which participates in the migration of glioma cells." (PMID 28837560, 2017). "Characterization of the resulting cell line (mGb4) by IF and FACS revealed that cells express CD15, CD133, CD44 stem cell markers together with SOX2 and OLIG2, two transcription factors associated with the maintenance of multipotency and proliferation of glioma multipotent cells." (PMID 26953813, 2016). "SPP1-CD44 interaction was shown to increase stemness of CD44-expressing glioma-initiating cells." (PMID 25658639, 2015). "Cholesterol depletion form human glioma cells using methyl-β-cyclodextrin (MβCD), an agent frequently used to disrupt lipid rafts, results in increased CD44 shedding, which was mediated by a transmembrane protease a disintegrin and metalloproteinase 10 (ADAM10)." (PMID 26347743, 2015). "Another downstream target of TGFβ, CD44, functions in glioma cell migration and invasion." (PMID 23951053, 2013). "Our results suggest that development of inhibitors which interfere with CD44-moesin interactions may open a new avenue in the future to mitigate cellular migration in gliomas." (PMID 23855374, 2013). "Our results suggest that development of inhibitors which interfere with CD44-moesin interactions may provide a means to counteracting cellular migration in gliomas." (PMID 23855374, 2013). "This study has revealed CD44 to exert a greater influence on glioma invasion than CD155." (PMID 22363471, 2012). "Our data suggest that CD44/CD155-KD significantly reduces glioma cell movement rate (p<0.0001)." (PMID 22363471, 2012). "The expression of CD44 identifies the ARPs and nearly all gliomas express this marker." (PMID 18398462, 2008). "However, high vascularization was observed in rat gliomas 101.8, which might lead to decreased expression of Epas1 and Cd44." (PMID 41009560, 2025). "Therefore, we might consider that ANXA5 supports multifarious malignant phenotypes of glioma cells through the MAPK/CD44 signaling pathway." (PMID 40607003, 2025). "ADAM17 may also promote the cleavage of intracellular CD44 and enhanced stemness in glioma cells." (PMID 40191733, 2025). "CD44, a multifunctional molecule, could not only promote the migration and invasion of glioblastoma cells under severe hypoxia but also serve as a prognostic biomarker in glioma patients with a poor prognosis." (PMID 40607003, 2025). "Corresponding to these data, the CD44 cell surface receptor is expressed by many immortalized human and rodent glioma cell lines, but its levels may vary dramatically, even between single cell-derived colonies of the same line, e.g., up to 20-fold for U-251 MG glioblastoma." (PMID 38672482, 2024). "Therefore, CD44 was responsible for glioma growth and progression." (PMID 36776876, 2023). "The expression of CD44 could reflect the evolution direction of glioma cells towards malignancy." (PMID 36776876, 2023). "Therefore, EMP3 and CHI3L1 may affect the proliferation, apoptosis, and death of glioma cells by regulating CD44 and affecting TGF-β, ERK, Akt, and other pathways." (PMID 37887529, 2023). "In addition, knocking down CD44 in glioma exosomes impaired the ability of glioma exosomes to induce XBP1s and miR-21 expression in BM-MSCs, indicating that glioma exosomal CD44 promoted XBP1s expression and upregulated cellular and exosomal miR-21 expression in MSCs." (PMID 37481646, 2023). "Besides, RUNX1/CD44 axis critically mediated the proliferation and migration of gliomas." (PMID 36776876, 2023). "Notably, few studies have focused on the immune characteristics of CD44 expression in glioma." (PMID 36776876, 2023). "The co-existence of differentiated non-stem glioma cells expressing CD44 may be the cause of such differences." (PMID 37760811, 2023).
glioma (continued). "Therefore, CD44 was proposed as a potential regulator of macrophage and immunotherapy in gliomas." (PMID 36776876, 2023). "Moreover, treatment with an anti-CD44 monoclonal antibody impeded glioma growth in mice." (PMID 35954411, 2022). "Next, we investigated, whether mutant glioma cells expressing high CD44 were prone to migration." (PMID 36348001, 2022). "Moreover, OPN might also regulate the mesenchymal phenotype of glioma by interacting with CD44 on tumor cells." (PMID 36036011, 2022). "However, on slices from CD44-/- mice, this phenotype could be detected only for a limited number of spheroids and for various glioma cell lines we observed disruption in invasiveness." (PMID 35992852, 2022). "Therefore, HAS3 and CD44 were chosen for further analysis of HA metabolism in glioma." (PMID 33986244, 2021). "However, the precise mechanisms underlying CD44-mediated glioma initiation and progression have not been completely elucidated." (PMID 35187044, 2021). "Here we found that the SPP1 gene mainly expresses in the macrophages rather than tumor cells, whereas the CD44 primarily expresses in the MES-like cells, suggesting that TAM-secreted OPN may regulate the mesenchymal phenotype of glioma by interacting with CD44 on tumor cells." (PMID 34805184, 2021). "We transfected the HAS3 siRNA or added CD44 antibody to U251 glioma cells to test this hypothesis." (PMID 33986244, 2021). "Therefore, CD44+ glioma cells participate in glioma immunosuppression." (PMID 35187044, 2021). "In addition, CD44+CD163+ cells were verified by IF on human glioma samples." (PMID 35187044, 2021). "Using U373-MG glioma cells in transwell invasion assay and time-lapse microscopy, the authors show that the migration speed and invasion properties of these cells in the presence of CD44/HA improves with increasing stiffness of the HA hydrogel in which they are cultured." (PMID 35127517, 2021). "Additionally, OPN induced radiation resistance by activating the CD44 signaling pathway in glioma." (PMID 34685653, 2021). "In addition, CD133 has been found to contribute to cell survival through regulating autophagy to enhance resistance in glioma cells, while CD44 may be involved in positive regulation in the Wnt signaling pathway for tumorigenesis." (PMID 34069945, 2021). "Thus, CD44+ malignant tumor cells, CD44+ TAMs, and CD44+ T cells may induce immunosuppression in glioma." (PMID 35187044, 2021). "Moreover, high CD44 expression was also found in low-grade glioma and glioblastoma tissues compared to normal brain tissues, with the CD44 expression level serving as a predictive marker for OS rate in low-grade glioma patients." (PMID 34944493, 2021). "Thus, the overall findings of our study conclude that CHSY1-mediated CS may promote CD44 activity and consequently regulate integrin expression in glioma cells, thereby serving as a potential pathway for therapeutic targeting in glioma." (PMID 34944101, 2021). "Finally, the correlation of CD44 mRNA expression and glioma immunotherapy was studied." (PMID 35187044, 2021). "Thus, coexpression of CD44 and checkpoint family members were checked in glioma, and we found that CD44 expression positively correlates with the expression level of PD-L1 and PD-1 and correlates with the expression level of PDCD1LG2 (namely PD-L2) as well in the TCGA and CGGA glioma datasets." (PMID 35187044, 2021). "Moreover, treating glioma cells with a C6S binding peptide also enhances the turnover of CD44." (PMID 34944101, 2021). "The potential association between higher tumor expression of CD44 and overall poor prognosis in patients with glioma could be explained by the roles of CD44 in the proliferation, invasion, metastasis of glioma, and resistance to chemotherapy and radiation therapy." (PMID 32232385, 2020). "Moreover, tumor expression of CD44 is shown to be up-regulated during glioma progression in the brain, which may aid in tracing and targeting the invading glioma cells." (PMID 32232385, 2020).
glioma (continued). "Fu and colleagues demonstrated that TG2 inhibition with monodansylcadaverine (MDC) suppresses cell proliferation and induces apoptosis in CD44+ glioma stem cells through the decrease of inhibitor of DNA binding 1 protein (ID1) and that this, therefore, may be a TG2 downstream regulator." (PMID 30691081, 2019). "Finally, CD44 was identified as a hit on all of the glioma cell lines." (PMID 31466397, 2019). "A recent study provided evidence that in the glioma perivascular niche osteopontin promotes stem cell-like properties and radiation resistance in adjacent cells via interaction with its receptor CD44 present on tumor cells and consequent activation of CD44 signaling." (PMID 30279357, 2018). "RNA analysis of GSCs also revealed increased expression of mesenchymal/stemness markers (Fibronectin, YLK-4, CD44 and Sox2) following treatment with IL-17, suggesting that IL-17 may play a role in altering the plasticity of gliomas by inducing ‘stemness’ or enhancing glial-mesenchymal transition." (PMID 26755664, 2016). "CD44 and TNFSF14 were significantly overexpressed in GBM compared to WHO Grade 3 glioma (confirmed by TCGA, CGGA, and Rembrandt), as well as LGG and normal brain tissue (confirmed by Rembrandt and qPCR analysis)." (PMID 39977830, 2025). "In glioblastoma, RFX1 was shown to negatively regulate the self-renewal capacity of glioma stem cells through direct FGF1 suppression, and to inhibit tumor invasiveness via downregulation of CD44." (PMID 41425715, 2025). "Studies highlight the importance of CD44, miRNA, and TGF-β signaling in tumor progression in glioma." (PMID 40943648, 2025). "Cluster of differentiation 44 (CD44) and tumor necrosis factor superfamily member 14 (TNFSF14) were found to be significantly overexpressed in GBM compared to lower-grade glioma (LGG) and normal brain tissue." (PMID 39977830, 2025). "SUV39H1 expression was positively correlated with the classic-like glioma subtype and markers such as NES and EGFR, with a lower correlation with mesenchymal-like markers like CD44 and CHI3L1." (PMID 40059829, 2025). "High CD29, CD44, and CD146 levels were also detected in EVs from two primary and one established high-grade glioma cell line, while CD133 was barely detectable in small EVs from all three cell lines." (PMID 40106404, 2025). "In TCGA glioma samples, USP14 showed positive correlation with CD44 and ALDH1A3, and inverse correlation with PN markers, SOX2 and OLIG2." (PMID 39990235, 2025). "The γ-secretase-cleaved intracellular domain of CD44 interacts with OPN that enriches stem cell phenotype and glioma growth through CBP/p300-dependent activation of HIF-2α." (PMID 39062100, 2024). "SRGN-expressing glioma cells after co-culture with mast cells further enhance their expression of SRGN, CD44, CXCL-10, CXCL-12 and TNFα as well as EMT-related genes ZEB-1 and vimentin." (PMID 38672477, 2024). "OPN, along with the stem cell marker CD44, shapes a perivascular niche that promotes the CSC phenotype and radiation resistance in glioma." (PMID 39062100, 2024). "Significant enrichment of the mesenchymal gene term and strong positive correlations between CD44 and the signature genes indicated that the IMRG‐based signature was an effective biomarker for mesenchymal gliomas." (PMID 37545464, 2024). "Specifically, CD44 was found in a perinecrotic, hypoxic niche with HIF-1α- and HIF-2α-positive glioma cells, as well as a perivascular, highly oxygenated niche with pseudo-hypoxic, HIF-2α-positive, stem-like cells." (PMID 39333557, 2024). "In glioma, cellular markers like CD133 and CD44 play a crucial role in identifying and characterizing CSCs, a subset of tumor cells with self-renewal ability and resistance to standard treatments." (PMID 38675202, 2024). "This interaction between CD44 and MMP9 facilitates glioma cell migration, which was also found to be highly enriched in mediating signal transduction in our study." (PMID 39033204, 2024).